AQP7B (aquaporin 7B)
Description:
Aquaglyceroporins form homotetrameric transmembrane channels, with each monomer independently mediating glycerol and water transport across the plasma membrane along their osmotic gradient.
Gene: Protein-coding gene on chromosome 2 (94,587,101 to 94,612,744, forward strand). Ensembl gene ENSG00000259916.
Subcellular location: Membrane
Subcellular location (Human Protein Atlas): Vesicles; Nuclear speckles; Nucleoplasm
Gene Ontology:
Molecular function: glycerol channel activity; urea transmembrane transporter activity; water channel activity; channel activity
Biological process: glycerol transmembrane transport; water transport; transmembrane transport; urea transmembrane transport
Cellular component: basolateral plasma membrane; membrane; plasma membrane
Genetic constraint (gnomAD): Loss-of-function variants: 20 observed, 15.65 expected, observed/expected ratio (o/e) 1.28, 90% interval 0.9 to 1.8. Missense variants: 376 observed, 294.75 expected, observed/expected ratio (o/e) 1.28, 90% interval 1.17 to 1.39. Synonymous variants: 129 observed, 112.16 expected, observed/expected ratio (o/e) 1.15, 90% interval 1 to 1.33.
Homologues: Orthologues: chimpanzee AQP7B (95% identical), macaque AQP7 (88% identical), guinea pig Aqp7 (69% identical), dog AQP7 (68% identical), mouse Aqp7 (60% identical), rat Aqp7 (51% identical), tropical clawed frog aqp7 (39% identical), zebrafish aqp7 (39% identical), Caenorhabditis elegans aqp-2 (28% identical), Drosophila melanogaster Eglp2 (14% identical), Drosophila melanogaster Eglp1 (14% identical), Drosophila melanogaster Eglp4 (14% identical), and 1 more. Paralogues in human: AQP7 (92% identical), AQP3 (35% identical), AQP9 (32% identical), AQP10 (31% identical), AQP2 (21% identical), AQP6 (20% identical), MIP (20% identical), AQP5 (18% identical), AQP4 (18% identical), AQP1 (18% identical), AQP8 (17% identical).